INS (insulin)
Diseases named in the same sentence as INS in open-access papers (continued):
Sharing a sentence is not in itself a finding about the gene and the disease.
Insulin resistance (continued). "However, the insulin secretion capacity is lower in Asians than Caucasians, and T2DM incidences are quickly rising in Asians with high insulin resistance." (PMID 37049581, 2023). "Insulin resistance is characterized by hyperinsulinemia and decreased expression of insulin-degrading enzyme (IDE)–Zn-metalloprotease, which is responsible for cleavage of insulin, amylin, and Aβ." (PMID 37895336, 2023). "HTGC values significantly correlated with both markers of insulin resistance: (TyG R = 0.36, p = 0.0252, HOMA2-IR: R = 0.69, p < 0.0001), and their components (fasting glucose: R = 0.51, p = 0.0008, fasting insulin: R = 0.66, p < 0.0001, fasting TG: R = 0.32, p = 0.0445)." (PMID 36944955, 2023). "Insulin resistance (IR) was analyzed by evaluating the homeostasis model assessment (HOMA) index, and HOMA-IR levels were calculated using the following equation: (fasting blood insulin [mIU/L] × blood glucose [mmol/L])/22.5." (PMID 38283741, 2023). "It has also been hypothesized that insulin levels may be more closely associated with glucose intolerance rather than with growth disturbances, and glucose intolerance may be present without overt macrosomia; likewise, mild macrosomia may be present without significant insulin resistance." (PMID 37176607, 2023). "A cohort study in non-diabetic individuals (relation between insulin sensitivity and RISC cardiovascular disease) proposed the existence of a causal relationship between insulin resistance and albuminuria." (PMID 37675359, 2023). "Adiponectin was also unaffected by kiwifruit ingestion, so that no adiponectin-mediated decrease in insulin resistance was likely, consistent with the observed stability in plasma glucose and insulin concentrations." (PMID 38231672, 2023). "In fact, they reduce hepatocyte insulin sensitivity by favoring the deposition of lipids in the liver, fibrosis, and steatosis (nonalcoholic fatty liver disease, NAFLD), which in turn worsens the state of insulin resistance." (PMID 37886939, 2023). "Fasting glucose levels were not significantly different, whereas fasting insulin levels and insulin resistance were increased in the CO patients (10.6 ± 5.8 vs 6.5 ± 2.8 miu/L, P = 0.019 and 2.11 ± 1.08 vs 1.4 ± 0.64, P = 0.038, respectively)." (PMID 37253232, 2023). "The estimates of insulin resistance derived from HOMA-IR are strongly correlated with estimates from the hyperinsulinaemic clamp (r=0.88), widely considered the gold standard for assessing insulin sensitivity." (PMID 36693633, 2023). "ApoC-III production is stimulated by insulin resistance, but ApoC-III itself amplifies insulin resistance through endothelial cells (ECs) by contributing to an impaired insulin signaling and endothelial dysfunction, acting as a key driver of the diabetic dyslipidemia." (PMID 36689070, 2023). "Our female mice, on the other hand, did not have increased insulin nor enlarged livers, which suggests there is perhaps a sex-specific protection against the development of insulin resistance." (PMID 37198225, 2023). "In the transduction pathway of insulin effect, any disruption in the PI3K/Akt signaling pathway may result in insulin resistance." (PMID 38138520, 2023). "These include signs of insulin resistance (abdominal obesity, acanthosis nigricans, hypertension or dyslipidemia) as well as the absence of autoantibodies and evidence of endogenous insulin secretion as shown by C-peptide levels." (PMID 36747290, 2023). "They found that insulin sensitivity and gonadotropin data in both HF with the descending 3β-HSD phenotype and classic PCOS indicated significant insulin resistance and LH hypersecretion in both suggesting that the descending 3β-HSD phenotype in HF is probably a variant of PCOS." (PMID 37217826, 2023). "Identifying dysregulated phosphosites common to multiple insults reveals subnetworks containing non-canonical regulators of insulin action, such as MARK2/3, and causal drivers of insulin resistance." (PMID 36808134, 2023).
Insulin resistance (continued). "Progressive worsening of the metabolic variables including DI, acute response to insulin (AIRg), insulin resistance, HOMA-IR (homeostatic model assessment for insulin resistance), fasting insulin, fasting glucose, and HBA1C (glycated hemoglobin) was observed (p for trend <0.05, mixed-model ANOVA)." (PMID 36982383, 2023). "Among individuals with insulin resistance, increased lipid deposition within muscle cells (intramyocellular lipids, IMCL) is associated with poor fatty acid oxidation, and decreased insulin sensitivity, independent of BMI." (PMID 37675136, 2023). "GDM occurs when maternal insulin resistance develops and/or progresses during gestation, and it is not compensated by a rise in maternal insulin secretion." (PMID 37765126, 2023). "The development of DM2 arises from a gradual decline in β-cell insulin secretion, primarily occurring in the presence of insulin resistance and metabolic syndrome and without the involvement of autoimmune factors." (PMID 37298632, 2023). "Furthermore, CAND1 KO+/--HFD mice developed more serve glucose intolerance and insulin resistance upon HFD challenge than WT-HFD mice, as revealed by the glucose tolerance test (GTT) and insulin tolerance test (ITT)." (PMID 37528093, 2023). "Since pioglitazone enhances the effects of circulating insulin (by decreasing insulin resistance), it does not lower blood glucose in animal models that lack endogenous insulin." (PMID 38004396, 2023). "The anti-IR experiment showed that insulin levels increased after HM475 intervention, and there were significant differences with the model group, indicating that HM475 could alleviate the insulin resistance of INS-1 cells stimulated by high glucose." (PMID 37175163, 2023). "A meta-analysis including five RCTs showed that the MD considerably decreased the frequency of gestational diabetes mellitus (GDM), Homeostatic Model Assessment for Insulin Resistance (HOMA-IR), insulin treatment, and gestational weight gain (GWG) than the regular intervention for pregnant mothers." (PMID 38201865, 2023). "Dependent variables included weight, body fat (BIA), VAT (DXA), MetS (BMI and WC), fasting glucose, 2 h glucose after oGTT, HbA1c, indices of insulin resistance (HOMA-IR, MATSUDA) and insulin secretion (ISSI-2, AUCins/glu and HOMA-B) measured during pregnancy and in the postpartum." (PMID 37891561, 2023). "Once insulin resistance takes place, not only does insulin no longer inhibit gluconeogenesis, but it also stimulates hepatic fat synthesis, both of which exacerbate insulin resistance and other symptoms." (PMID 38201855, 2023). "We previously showed that compared to the mice fed a LFD, the mice fed a HFD diet exhibited impaired glucose tolerance and insulin resistance with no increase in serum insulin concentration in obese mice." (PMID 36674494, 2023). "The mechanisms underpinning skeletal muscle insulin resistance are not fully resolved, but there is evidence that impairment of insulin‐facilitated skeletal muscle glucose transport occurs distal to IR‐Akt signaling." (PMID 36807886, 2023). "Furthermore, higher basal insulin resistance (HOMA-R) and lower dynamic insulin sensitivity (QUICKI, OGIS 2 h, ISIcomp, MCRest, Si (oral), and PREDIM) were observed in this group." (PMID 37238949, 2023). "High fat diet promotes insulin resistance in mice but does not trigger pancreatic beta cell death or reduced insulin production." (PMID 37730757, 2023). "As expected, insulin resistance was confirmed by reduced pAkt activation following insulin stimulation, though no main effect of GW was observed." (PMID 37325367, 2023). "It is characterized by hyperglycemia attributed to either a lack of insulin (Type I DM), peripheral insulin resistance and/or insufficient insulin synthesis (Type I DM)." (PMID 37443710, 2023). "When a standardized insulin assay is lacking, 3 relatively basic metabolic markers can help identify insulin resistance." (PMID 37818160, 2023).
Insulin resistance (continued). "This means that cells that do not take up glucose in insulin resistance, are still affected by the insulin signalling via its other pathways—PI3K and MAPK." (PMID 37760052, 2023). "Nonetheless, studies show that GiA-1 is not the main source of active compounds, and there are other nonpolar components of compounds with anti-insulin-resistance and insulin-mimetic activities in GIE." (PMID 37297501, 2023). "Interventions that recapitulate causes of insulin resistance in humans, including hyperinsulinemia (chronic incubation with insulin, CI), chronic inflammation (TNF-α) and Cushing’s syndrome/inflammatory steroids (dexamethasone, DEX) have been used to model insulin resistance in 3T3-L1 adipocytes." (PMID 36283703, 2023). "While no medication specifically targets insulin resistance, several antidiabetic drugs, including insulin sensitizers, insulin secretagogues, and alpha-glucosidase inhibitors, have been utilized to improve insulin resistance." (PMID 38053837, 2023). "Overactive mTOR and its resistance to insulin stimulation are considered pathological features of AD that represent insulin resistance independent of type-2 diabetes, along with impaired insulin receptor function in AD postmortem brain." (PMID 37457922, 2023). "In the insulin resistance state, there is a disruption in the Protein Kinase B (Akt)/Phosphoinositide 3-kinase (PI3K)/Insulin receptor substrate 1 (IRS-1) signaling pathway as an insulin response pathway." (PMID 37508403, 2023). "Second, MMP7 expression levels (and of COL6A3 encoding collagen VI alpha) were found to be increased in ScWAT of obese insulin resistant subjects as compared with obese-insulin sensitive subjects, suggesting an involvement of MMP7 in obesity, ECM remodeling and insulin resistance." (PMID 37445827, 2023). "Many patients with a similar degree of liver steatosis exhibit distinct insulin sensitivity (very high or very low) and improvement of insulin resistance does not necessarily reverse liver steatosis." (PMID 36836874, 2023). "Tisp40 overexpression did not affect fasting blood glucose, serum insulin, homeostastic model assessment–insulin resistance (HOMA-IR) index, serum triglyceride and total cholesterol levels in mice." (PMID 37291168, 2023). "In addition, liver functions were improved by O. aristatus, as indicated by a reduction in the serum levels of glucose, insulin and HOMA-IR, indicating a significant decrease in insulin resistance." (PMID 36678606, 2023). "Elevated insulin levels and higher HOMA-IR indices in the SZ group could suggest a link between schizophrenia and metabolic syndromes like insulin resistance." (PMID 38139760, 2023). "Elevated levels of free fatty acids, proinflammatory cytokines, and intermediary lipids, such as ceramides, in non-adipose tissues, contribute to impaired insulin signaling and a state of insulin resistance." (PMID 38138997, 2023). "GABA alleviated obesity-induced increases in fasting blood glucose, improved glucose tolerance and insulin resistance, and improved the serum lipid profile, including decreased TG, TC, and LDL and increased HDL, suggesting that GABA improves insulin sensitivity." (PMID 37681878, 2023). "Although HFD increased insulin levels, it did not reduce fasting glucose, indicating the presence of insulin resistance." (PMID 37176029, 2023). "Overall, in this study, we reveal that ZFYVE28 is involved in insulin resistance by promoting phosphorylated insulin receptor degradation, and ZFYVE28 may be a potential therapeutic target to improve insulin sensitivity." (PMID 37884540, 2023). "Furthermore, a significant action in interfering with insulin signaling and insulin-stimulated glucose uptake is pursued by interferon-gamma (IFN-γ), eventually leading to insulin resistance and DM." (PMID 37239990, 2023). "Second, we utilized HOMA-IR as an indicator for insulin resistance but did not perform an insulin clamp study." (PMID 37591864, 2023).
Insulin resistance (continued). "For example, deactivation of the kinase GSK3 by insulin was impaired in multiple 3T3-L1 adipocyte and mouse adipose tissue models of insulin resistance, and was not entirely attributable to reduced deactivation by Akt." (PMID 37248992, 2023). "Fasting blood glucose and insulin levels increased by HFD were diminished by the administration of 3-OH phloretin, suggesting that 3-OH phloretin may alleviate obesity-induced insulin resistance." (PMID 36838843, 2023). "Despite these strong effects on hepatic lipid content, SH42 did not affect fasting plasma glucose, insulin, or homeostatic Model Assessment for Insulin Resistance (HOMA‐IR) scores (Fig EV1H–J)." (PMID 37357756, 2023). "It has been proposed that As-induced alterations in insulin secretion mainly contribute to impaired carbohydrate metabolism rather than peripheral insulin resistance." (PMID 37624175, 2023). "CREB knockdown in macrophages could downregulate M2 marker genes, then improve insulin resistance, suggesting that CREB is important in maintaining insulin sensitivity in white adipose tissue via its initiation of the innate immune system." (PMID 37880674, 2023). "We found that HFD-STZ mice had hyperglycemia, elevated total and LDL cholesterol, glucose intolerance, insulin resistance, and they did not produce insulin." (PMID 37730757, 2023). "Here, the authors show that ZFYVE28 is involved in insulin resistance by promoting the degradation of phosphorylated insulin receptor and ZFYVE28 may be a potential therapeutic target to improve insulin sensitivity." (PMID 37884540, 2023). "T2DM is the result of the dysfunctioning of β cells of the pancreas leading either to improper utilization of insulin or its abnormal secretion because of an imbalance between insulin levels and insulin sensitivity, and hence T2DM is also referred to as “insulin resistance”." (PMID 36811724, 2023). "However, there were significantly higher levels of glucose (p = 0.010), insulin (p < 0.001), and HOMA-IR (p = 0.008) in the overweight/obese children, with an average insulin resistance increase of 89%." (PMID 36678200, 2023). "The role of insulin resistance can contribute to the conversion to T2D if insulin secretion does not compensate insulin resistance." (PMID 37795366, 2023). "When the Cm and C were compared, it was found that all post‐intervention anthropometric measurements were similar, but the percentage of decrease in fasting blood glucose, fasting insulin, and HOMA‐IR (Homeostasis Model Assessment‐Insulin Resistance) values were greater in C (p < .05)." (PMID 38107130, 2023). "Type 2 diabetes patients often have endogenous hyperinsulinemia due to insulin resistance, while type 1 diabetes patients often experience hyperinsulinemia due to exogenous insulin therapy even though they do not secrete insulin endogenously." (PMID 37101201, 2023). "Amongst insulin based surrogate indices of insulin resistance, significant negative correlation was observed for the InsuTAG index with the McAuley index (r − 0.65, p < 0.01,) the QUICKI (r − 0.34, p < 0.01) and the FGIR (r − 0.35, p < 0.01)." (PMID 37945732, 2023). "In this studied population, patients with CP (but not with AP) demonstrated insulin resistance and altered insulin function, as shown by the HOMA hyperbolic product." (PMID 36651310, 2023). "Similarly, in individuals with obesity and insulin resistance, ADF reduced fasting insulin and HOMA-IR at 6 and 12 months compared to continuous calorie restriction, regardless of weight loss, which was similar for both groups." (PMID 37296485, 2023). "T2DM is characterized by the existence of tissue insulin resistance (IR), a deficit in insulin secretion, and a lack of compensatory responses to insulin secretion." (PMID 37274075, 2023). "While these molecular events can occur, evidence suggests that defects in proximal insulin signalling are not the major determinant of insulin resistance." (PMID 37248992, 2023).
Insulin resistance (continued). "While on T2DM, the patient experiences high blood sugar, insulin resistance, and a relative lack of insulin." (PMID 37175192, 2023). "Lastly, we found CNS insulin resistance, as defined by impaired insulin signaling through administration of ICV S961, decreased insulin BBB interactions in both male (binding) and female (transport) mice and that these effects may be regionally regulated." (PMID 37076875, 2023). "Although several studies have observed an increase in insulin levels and greater insulin resistance in SGA children compared to AGA peers, not all of them have found a consensual increase in fasting glucose levels." (PMID 37342257, 2023). "Our study provides evidence that drugs that normalize intracellular Ca2+ homeostasis can ameliorate insulin resistance by rescuing impaired phosphorylation of AKT, an essential kinase for insulin signaling, and its downstream signaling molecules in the setting of obesity and hyperlipidemia." (PMID 37121975, 2023). "Most risk variants for T2D in healthy populations act through impairing insulin secretion and, consequently, β-cell dysfunction rather than insulin action that results in insulin resistance." (PMID 36976988, 2023). "T2DM is a chronic metabolic disorder that is characterized by hyperglycemia in the context of insulin resistance (IR) and relative lack of insulin." (PMID 37238949, 2023). "Additionally, insulin resistance and hyperinsulinemia seem to be involved in the etiology of CRC through the mitogenic action of insulin, which stimulates cell proliferation and inhibits apoptosis." (PMID 38082394, 2023). "Furthermore, tyrosine phosphatase 1B (PTP1B), a protein known to inhibit insulin action by dephosphorylating IR, was activated, and PTP1B inhibition canceled HCI-induced insulin resistance." (PMID 37389126, 2023). "In general, they report a possible correlation with phthalate exposure, with these contaminants affecting several glucose metabolism parameters (glucose and insulin levels, insulin tolerance, HOMA-IR, HbA1c, β-cell function) that will lead to insulin resistance.." (PMID 37367903, 2023). "After 1-week CORT treatment, when CORT-induced hyperinsulinemia and its reduction in GR-mKO mice were already observed, an intraperitoneal insulin tolerance test (IPITT) implied CORT-induced insulin resistance had not improved in GR-mKO mice." (PMID 36917179, 2023). "At a point when overt impaired glucose sensing and insufficient β-cell mass ensues, insulin secretion fails to compensate for increased insulin resistance then impaired glucose tolerance and T2D develops." (PMID 36993818, 2023). "Empagliflozin significantly improved insulin sensitivity indexes but did not impact insulin resistance and β-cell function." (PMID 37568149, 2023). "In individuals with newly diagnosed diabetes mellitus, it is not easy to estimate the levels of insulin production and insulin resistance." (PMID 37664380, 2023). "Being younger, prepubertal, having relatively low BMI, low waist/hip ratio, low insulin resistance (HOMA-IR) index, high high-density lipoprotein, low triglyceride, low fasting insulin and glucose levels, low uric acid and low alanine transaminase (ALT) levels were associated with MHO." (PMID 37038589, 2023). "Insulin signaling is mainly disrupted by inflammation, ER stress, oxidative stress, the activation of the JNK and NF-кB pathways, and the increase of skeletal muscle insulin resistance." (PMID 37876013, 2023). "Likewise, adipose insulin resistance, indexed as plasma [NEFA] × [insulin], was increased in all NAFL groups." (PMID 36928190, 2023). "Interestingly, experimental insulin resistance was also observed to increase GLUT4 clustering, suggesting a link between the clustering ability of GLUT4 and insulin sensitivity." (PMID 37791639, 2023).